IRF9 (interferon regulatory factor 9)
Diseases named in the same sentence as IRF9 in open-access papers (continued):
Sharing a sentence is not in itself a finding about the gene and the disease.
melanoma (11 papers, 2018 to 2025). A malignant, usually aggressive tumor composed of atypical, neoplastic melanocytes. "In line with this evidence, STAT2 and its companion IRF9 were found to mediate resistance to BRAFi and to be associated with amoeboid phenotype in melanoma." (PMID 37408506, 2023). "Loss of STAG2 in melanoma results in IRF9 activation, which in turn upregulates PD-L1 expression in cancer cells, suggesting a potential tumor suppressor function of STAG2 in immune evasion." (PMID 35388001, 2022). "Knocking down IRF9 or STAT2 in melanoma cell lines A375 and SK-MEL-28 induces GSDME-dependent pyroptosis and restores sensitivity to BRAFi." (PMID 37373523, 2023). "H3K27ac HiChIP analyses identified interferon regulatory factor 9 (IRF9) as a major direct target of stromal antigen 2 (STAG2) in melanoma cells." (PMID 36768307, 2023). "We further identify Interferon Regulatory Factor 9 (IRF9) as a major direct target of STAG2 in melanoma cells via integrated RNA-seq, STAG2 ChIP-seq and H3K27ac HiChIP analyses." (PMID 35388001, 2022). "We confirmed knockdown of STAG2 increased levels of IRF9 expression in multiple melanoma cell lines." (PMID 35388001, 2022). "Lastly, our identification of IRF9 as a key target of STAG2 in the context of 3D genome organization in melanoma cells raises the possibility that upregulation of type I interferon signaling may contribute to the tumor suppressor function of STAG2." (PMID 35388001, 2022). "We focused on characterizing IRF9 as a direct target of STAG2 in melanoma cells, because that IRF9 is a central transcription factor in type I interferon signaling pathway and that motifs of several IRF family members were found to be enriched in the enhanced H3K27ac loop anchors." (PMID 35388001, 2022). "Targeting IRF9/STAT2 may prevent BRAFis resistance in melanoma by inducing pyroptosis." (PMID 39802949, 2024). "Moreover, the sustained activation of type I interferon signalling in response to IFNβ mediated by the Stat1/Stat2/IRF9 complex enhances the round amoeboid phenotype in melanoma cells, whereas its downregulation by various approaches promotes the mesenchymal invasive phenotype." (PMID 32872349, 2020). "IRF9 and STAT2, which are part of the Jak-STAT pathway, play a major role in BRAFi resistance in melanoma." (PMID 37373523, 2023). "Here, we show that IRF9, a key component in the type I interferon signaling pathway, is a direct target of STAG2 in melanoma through integrated analyses of RNA-Seq, ChIP-seq, and H3K27ac HiChIP." (PMID 35388001, 2022). "Targeting IRF9/STAT2 may offer a promising strategy to prevent melanoma resistance to BRAFis by regulating pyroptosis, leading to the durable regression of melanoma in an immune-mediated manner." (PMID 37373523, 2023). "Since IFN signaling and IRF9 in particular play critical roles in regulating the expression of PD-L1 in cancer cells, we examined whether STAG2 modulates the expression of PD-L1 in melanoma cells." (PMID 35388001, 2022).
cardiac hypertrophy (9 papers, 2014 to 2024). "Cardiac-specific overexpression of IRF9 attenuated cardiac hypertrophy whereas hypertrophy, fibrosis and cardiac dysfunction were augmented in IRF9 knockout mice." (PMID 38665231, 2024). "This study identified IRF9 as a negative regulator of left ventricular pressure overload-induced cardiac hypertrophy and showed that IRF9 level is significantly elevated in TAC-induced murine hearts." (PMID 34831061, 2021). "This is in line with previous studies demonstrating an IRF9 involvement in FA metabolism, insulin resistance, cardiac hypertrophy and hepatic-ischemia-reperfusion injury." (PMID 34237114, 2021). "Collectively, these results clearly demonstrate the involvement of acetyltransferase p300 in positive regulator myocardin- and negative regulator IRF9-modulated cardiac hypertrophy in response to ventricular pressure overload." (PMID 34831061, 2021). "Furthermore, transgenic mice overexpressing IRF9 are protected from left ventricular pressure overload-induced pathological cardiac hypertrophy." (PMID 34831061, 2021). "Similarly, other regulators such as NGF1A‐binding protein, inducible cAMP early repressor, and interferon regulatory factor 9 play inhibitory roles in cardiac hypertrophy, and the expression of these molecules all increases in response to hypertrophic stimuli." (PMID 31532577, 2019). "Consistently, an aggravated cardiac hypertrophy occurs in Irf9−/− mice." (PMID 28184222, 2017). "Recent reports found that IRF3, IRF7, and IRF9 protect against cardiac hypertrophy." (PMID 28184222, 2017).
influenza (9 papers, 2010 to 2024). An acute viral infection of the respiratory tract, occurring in isolated cases, in epidemics, or in pandemics; it is caused by serologically different strains of viruses (influenzaviruses) designated A, B, and C, has a 3-day incubation period, and usually lasts for 3 to 10 days. "AR IRF9 deficiency has been reported in 3 children from 2 kindreds suffering from influenza pneumonia, recurrent infections, and disseminated disease after inoculation with LAVs (MMR and varicella zoster virus [VZV])." (PMID 36976641, 2023). "Recently, life-threatening influenza was also reported in a child with autosomal recessive (AR) homozygous IRF9 deficiency." (PMID 30671054, 2018). "The first breakthrough emerged from a study testing the hypothesis that candidate inborn errors of TLR3-, IRF7-, and IRF9-dependent type I IFN immunity previously shown to underlie life-threatening influenza pneumonia might also underlie critical COVID-19." (PMID 37196358, 2023). "In addition to IRF7 and IRF9 deficiency predisposing to severe influenza, a RIG-I variant has also been described in an adult patient with severe influenza." (PMID 30671054, 2018). "AR IRF9 deficiency, AR IRF7 deficiency, AD TLR3, and AR IFNAR2 deficiency also underlie influenza pneumonia." (PMID 36976641, 2023). "Genes such as Irf7, Irf9, Mx1, Ifit3, Oas1a (L5) were induced most highly in lungs of virally infected mice (influenza and RSV)." (PMID 31253760, 2019). "These diseases encompass herpes simplex encephalitis (HSE) and severe influenza in IRF3- and IRF7/IRF9 deficiency, respectively." (PMID 30671054, 2018). "The causal relationship between homozygous IRF9 deficiency and increased susceptibility to influenza was convincingly demonstrated by the rescue of IFN responses and control of viral replication after expression of wt IRF9 in patient cells." (PMID 30671054, 2018). "These cases revealed the indispensable role of human intrinsic (TLR3, IRF7, IRF9, STAT1, and STAT2 in RECs, in which the virus replicates) and innate (IRF7 in plasmacytoid dendritic cells, in which the virus does not replicate) type I and III IFN immunity in host defense against influenza." (PMID 36112363, 2022).
lupus (7 papers, 2018 to 2025). "On the other hand, monocytes of systemic lupus erythematosus patients have reduced level of miR-302d expression, resulting in increased IRF9 expression." (PMID 30147694, 2018). "Increased expression of type I IFNs and ISGs are among the hallmarks of lupus disease progression, consequently leading to high production of IRF9-mediated IgG autoantibodies." (PMID 30147694, 2018). "Nineteen probes for 16 lupus-relevant genes (Abca1, Apobec3, Ccr7, Ceacam3, Ets1, Foxp3, Hdac1, Ifng, Irf9, Itgam, Jhdm1d, Mmp9, Oscar, Slc4a1, Tbx21, and Tlr7) were identified from the database of male murine spleen." (PMID 30246031, 2018). "In addition to mediating antiviral responses, IRF9 is also elevated in autoimmune diseases, such as systemic lupus erythematosus and rheumatoid arthritis." (PMID 39958336, 2025). "In contrast, miR-302d appears at lower levels in plasma of experimental autoimmune encephalomyelitis mouse model and systemic lupus erythematosus and regulates IFN type I gene expression targeting interferon regulator factor-9 (IRF-9) in murine model." (PMID 30949455, 2019).
autoimmune disease (6 papers, 2017 to 2025). A disorder resulting from loss of function or tissue destruction of an organ or multiple organs, arising from humoral or cellular immune responses of the individual to their own tissue constituents. "Finally, to investigate the association between the IRF9-regulated ISGs expression in sgScd2 Th1 cells and autoimmune diseases, we focused on the expression levels of ISGs that are elevated in patients with SLE." (PMID 36059459, 2022). "Previous studies have demonstrated the crucial role of IRF9 in inflammation, autoimmune diseases like SLE, cardiovascular diseases, cell proliferation and immune cell regulation." (PMID 33936086, 2021). "Using a ChIP-seq analysis, we also revealed genome wide binding profiles of IRF9 in sgScd2 Th1 cells and found that IRF9 bound to the regulatory region of ISGs, the expression levels of which are characteristically elevated in patients with autoimmune diseases." (PMID 36059459, 2022). "STAT1, STAT2, and IRF9 amplify the JAK-STAT signaling pathway to enhance the IFN response, and the JAK-STAT pathway transduces intracellular signals for various cytokines, which is crucial for the pathogenesis of autoimmune diseases." (PMID 41181153, 2025). "IRF9 is also involved in regulating cell proliferation, tumor formation, cardiovascular disease, inflammation, autoimmune disease, and immune cell regulation, some of which is not related to ISGF3 complex." (PMID 30147694, 2018).
lung carcinoma (6 papers, 2016 to 2025). "Kaplan–Meier curve analysis for lung cancer survival revealed that high IRF9 expression levels were found to be associated with lower overall survival in patients with lung cancer (HR = 1.21, p = 0.0031) and LUAD patients (HR = 1.82, p < 0.001)." (PMID 33430083, 2021). "IRF9 is frequently overexpressed in human lung cancer and is associated with decreased patient survival; however, the underlying mechanisms remain to be elucidated." (PMID 33430083, 2021). "IRF9 increases versican expression,which is associated with poor survival in lung cancer patients." (PMID 39384770, 2024). "Similar oncogenic properties of IRF9 have been reported in other tumor types, including lung cancer, colorectal cancer and myeloid leukemia." (PMID 41403935, 2025). "For instance, a previous study investigating lung cancer found that interferon-β (IFN-β) induced the upregulation of PDL1 in lung cancer cells via the activation of the IRF9 pathway." (PMID 35664436, 2022). "In this study, we investigated the role of the transcription factor interferon regulatory factor 9 (IRF9) in the IFN pathway in lung cancer." (PMID 33430083, 2021). "In both patients with lung cancer and LUAD patients, Kaplan–Meier curves showed that reduced survival was associated with IRF9 overexpression." (PMID 33430083, 2021). "In these circumstances, it is reasonable that Kaplan–Meier curves show lower overall survival of patients with lung cancer when IRF9 expression is high." (PMID 33430083, 2021). "In the present study, in which we focused on lung cancer cells, IRF9 clearly promoted cell proliferation, migration, and tumor growth." (PMID 33430083, 2021). "Based on the human lung cancer data, a positive correlation was found between IRF9 and VCAN expression." (PMID 33430083, 2021). "Together with STAT2 and p65, IRF9 enhances lung cancer cell growth and, in pancreatitis, promotes proliferation and migration." (PMID 33430083, 2021). "On analyzing data from The Cancer Genome Atlas (TCGA), we found expression levels of IRF9, STAT1, and STAT2 in patients with lung cancer, and IRF9 expression levels were positively correlated with those of STAT1 and STAT2." (PMID 33430083, 2021). "We stained a tissue microarray obtained from patients with lung cancer and found that IRF9 was expressed in both tumor and stromal cells in different types of lung cancers, including LUAD, adenosquamous cell carcinoma, squamous cell carcinoma, small-cell carcinoma, and bronchioloalveolar carcinoma." (PMID 33430083, 2021). "In this study, we showed for the first time the oncogenic effects of IRF9 in lung cancer." (PMID 33430083, 2021). "Conversely, IRF5, IRF6, IRF7, and IRF9 may induce lung cancer progression." (PMID 39384770, 2024). "However, the mechanism by which IRF9 influences tumor development and progression in lung cancer remains unclear." (PMID 33430083, 2021). "According to PAH GRN analysis, IRF9 is capable of regulating LINC01089 expression along with 189 other PAH common DEGs, which are known to be co-expressed in lung cancer models and are related to retromer complex binding." (PMID 39791702, 2024). "For the first time, we showed the direct binding of IRF9 to the promoter of VCAN as well as a correlation between IRF9 and VCAN expression in lung cancer." (PMID 33430083, 2021). "The targeted inhibition of IRF9 in lung cancer could therefore be used as a new treatment option without multimodal interference in microenvironment JAK-STAT signaling." (PMID 33430083, 2021). "Indeed, we demonstrated the IRF9-dependent regulation of VCAN for the first time and showed that CDKN1A might be involved in lung cancer development and progression." (PMID 33430083, 2021).
breast tumor (5 papers, 2004 to 2024). "IRF9 is not only associated with the development of resistance to antimicrotubule agents in breast tumor cells, but is also reported as potential link to downstream mediators of IFN signaling to drug resistance in human cancers." (PMID 38632500, 2024). "The observation that tumor inherent type I IFN signaling may be driving immune chemotherapeutic response and anti-tumor immunity led us to consider the potential reversibility of IRF9/IFN loss in human breast tumors, as a possible means for enhanced therapeutic response and prolonged survival." (PMID 31482136, 2019). "We had also previously observed an inverse correlation between IRF9 and ErbB2 expression in a panel of breast tumor cell lines." (PMID 28174229, 2017).
colorectal cancer (5 papers, 2019 to 2025). A primary or metastatic malignant neoplasm that affects the colon or rectum. "We also investigated the activation and expression of STAT3 and IRF9 in 2D compared to 3D cultures in the colorectal cancer cell line DLD1." (PMID 30679726, 2019). "Although this data does not implicate a causal relationship, it further suggests a connection between STAT3 and IRF9 expression in colorectal cancer." (PMID 30679726, 2019). "In summary, our data indicates a connection between STAT3 and IRF9 in colorectal cancer." (PMID 30679726, 2019). "Although the exact mechanism by which STAT2 promotes colorectal cancer remains to be determined, there is some mechanistic evidence that STAT2 can act outside the canonical IFNAR1-STAT2/STAT1/IRF9 axis via unphosphorylated STAT2." (PMID 41440237, 2025). "Oncogenic KRAS was shown to inhibit the expression of STAT1, STAT2 and IRF9 (members of the ISGF3 transcription-promoting complex); thus, hampering the basal and IFN-induced expression of ISGs in colorectal cancer cell lines." (PMID 33668131, 2021). "We previously showed that STAT1, STAT2 and IRF9, along with a majority of the IRDS genes, were induced in HCT116 colorectal carcinoma cells grown as MCS14." (PMID 30679726, 2019). "In this study we found that transcription factor STAT3 is activated upstream of IRF9 and binds to the IRF9 promoter in MCS of HCT116 colorectal carcinoma cells." (PMID 30679726, 2019).
colitis (4 papers, 2019 to 2024). Inflammation of the colon. "We found that mice deficient in IRF9 developed fewer tumors compared with their corresponding WT littermates in the mouse model of AOM/DSS-induced colitis-associated CRC." (PMID 35205671, 2022). "We subjected cohorts of WT and Irf9−/− littermate mice to an AOM injection followed by a single round of DSS to induce colitis." (PMID 35205671, 2022). "Overall, these data suggest that IRF9 promotes DSS-induced colitis." (PMID 35205671, 2022). "During dextran sodium sulfate- (DSS-) induced colon inflammation and IFN-γ-treated macrophages, STAT1/IRF9 complex played a proinflammatory effect by regulating the transcription of CXCL10 gene." (PMID 34249133, 2021). "Notably, we observed a population of Tregs with high expression of ISGs (e.g., Irf7, Irf9, Isg15) from mesenteric lymph nodes (MLNs) during dinitrobenzenesulfonic acid (DNBS)–induced colitis." (PMID 38085267, 2024).
gastric cancer (4 papers, 2020 to 2024). A primary or metastatic malignant neoplasm involving the stomach. "ADAR (an interferon-inducible RNA-editing enzyme) mitigates IFN signaling in gastric carcinoma through down-regulating STAT1 and IRF9 by miR-302a." (PMID 37408777, 2023). "Adenosine deaminase acting on RNA (ADAR1) was reported to block the transport of ISGF3 into the nucleus by upregulating miRNA-302a and thereby targeting IRF9 and STAT1 in gastric cancer." (PMID 36104718, 2022). "Hence, our results suggest that ADAR1 regulates IFN signaling in gastric cancer through the suppression of STAT1 and IRF9 via miR-302a, which is independent from the RNA editing of known IFN production pathway." (PMID 32867271, 2020). "Since miR-302a-3p can target IRF9 by directly binding to its 3′UTR and miR-302-5p can weakly bind to STAT1 and indirectly regulate its expression, ADAR1-mediated miR-302a regulation might influence gastric cancer in an integrative manner." (PMID 38689093, 2024).
HCMV infection (4 papers, 2014 to 2021). "Another report showed that human cytomegalovirus infection can activate the type I IFN signaling pathway, which enhances viperin transcription through the STAT1/STAT2/IRF-9 complex termed ISG factor 3 (ISGF3) by binding to the promoter response element ISRE." (PMID 27232627, 2016). "We confirmed known effects of HCMV infection on Jak1, STAT2, and IRF9 and demonstrated that, apart from STAT1, expression of the final effectors in both interferon induction and response pathways were all progressively diminished during infection." (PMID 24906157, 2014). "Phosphorylation levels of IRF9, STAT1, and STAT2 were shown to decrease after HCMV infection." (PMID 34305856, 2021).
Immunodeficiency (4 papers, 2009 to 2023). Failure of the immune system to protect the body adequately from infection, due to the absence or insufficiency of some component process or substance. "We found multiple genes with ClinVar variants from patients with primary immune deficiencies (for example, IRF9, IRF7, STAT1, STAT2) that are not GWAS-linked genes but are in their network vicinity, providing evidence of the importance of this gene module for these diseases." (PMID 36823319, 2023). "According to the OMIM (Online Mendelian Inheritance in Man) database, ISG15, IRF9, and STAT1 are related to immunodeficiency." (PMID 38113079, 2023).
colon carcinoma (3 papers, 2019 to 2024). "We previously identified interferon regulatory factor 9 (IRF9) to be responsible for the up-regulation of a subset of interferon (IFN)-stimulated genes (ISGs) in MCS of colon carcinoma cells." (PMID 30679726, 2019). "IRF9, the primary DNA-binding protein of ISGF3, has been shown to contribute to anticancer drug resistance (including cisplatin resistance) in colon cancer by upregulating IRDS genes." (PMID 39062738, 2024). "To further confirm the tumor-promoting role of IRF9 in CRC, we used a spontaneous mouse model of colon cancer." (PMID 35205671, 2022). "Hence, we sought out to test if JAKs were involved in the activation of STAT3 in MCS of colon cancer cells and whether JAK-inhibition can affect induction of IRF9 and the panel of IRDS genes." (PMID 30679726, 2019).